RIMBP2 (RIMS binding protein 2)
Description:
Plays a role in the synaptic transmission as bifunctional linker that interacts simultaneously with RIMS1, RIMS2, CACNA1D and CACNA1B.
Synonyms: RIM-BP2; KIAA0318; RBP2; MGC15831; PPP1R133
Tractability: Antibody: UniProt places it where antibodies can reach, with medium confidence; its Gene Ontology location is reachable by antibodies, with medium confidence. PROTAC: ubiquitination databases record sites on it; its protein half-life has been measured.
Gene: Protein-coding gene on chromosome 12 (130,396,131 to 130,768,228, reverse strand). Ensembl gene ENSG00000060709.
Subcellular location: Cell membrane; Synapse
Subcellular location (Human Protein Atlas): Nucleoplasm; Cytosol; Golgi apparatus
Gene Ontology:
Biological process: neuromuscular synaptic transmission
Cellular component: plasma membrane; synapse
Genetic constraint (gnomAD): Loss-of-function variants: 45 observed, 97.54 expected, observed/expected ratio (o/e) 0.46, 90% interval 0.36 to 0.59. The upper end of that interval is the gene's LOEUF score, 0.59, which puts it in group 2 of 6, group 1 being the genes least tolerant of losing a copy. Missense variants: 1,494 observed, 1,677.2 expected, observed/expected ratio (o/e) 0.89, 90% interval 0.85 to 0.93. Synonymous variants: 747 observed, 707.7 expected, observed/expected ratio (o/e) 1.06, 90% interval 0.99 to 1.12.
Homologues: Orthologues: chimpanzee RIMBP2 (99% identical), macaque RIMBP2 (98% identical), pig RIMBP2 (84% identical), dog RIMBP2 (80% identical), rat Rimbp2 (79% identical), mouse Rimbp2 (78% identical), tropical clawed frog rimbp2 (68% identical), rabbit RIMBP2 (56% identical), zebrafish rimbp2b (53% identical), guinea pig RIMBP2 (50% identical), zebrafish rimbp2a (47% identical), Drosophila melanogaster Rbp (26% identical), and 1 more. Paralogues in human: TSPOAP1 (34% identical), RIMBP3C (20% identical), RIMBP3B (20% identical), RIMBP3 (20% identical).
Diseases named in the same sentence as RIMBP2 in open-access papers:
RIMBP2 is named in the same sentence as 14 diseases in open-access papers, as found by Europe PMC text mining. Sharing a sentence is not in itself a finding about the gene and the disease. The quoted sentences say what the papers report.
lung squamous cell carcinoma (2 papers, 2022 to 2023). "Among these mutations, a mutation was identified within the enhancer of the RIMBP2 gene, which was reported to correlate with more favorable prognosis in lung squamous cell carcinoma patients." (PMID 35449156, 2022). "In this study, SCLC patients with low expression of RIMBP2 (RIMS Binding Protein 2), a protein predicted to be involved in neuromuscular synaptic transmission, had a poor prognosis, consistent with results previously obtained in lung squamous cell carcinoma patients." (PMID 37958393, 2023).
bruxism (1 paper, 2024). Excessive clenching of the jaw and grinding of the teeth. "The second region was identified on chromosome 12, near the RIMS Binding Protein 2 (RIMBP2) gene; individuals carrying the T allele of the top SNP rs571497947 had a risk of bruxism 3.495 times higher than individuals with the TGGGGGGA allele sequence." (PMID 38397906, 2024). "Taking advantage of this approach, in this study, three novel candidate genes, i.e., NLGN1, RIMBP2, and LHFP, were identified as potential risk loci for bruxism." (PMID 38397906, 2024).
deafness (1 paper, 2014). An inherited or acquired condition characterized by the complete loss of the ability to hear from one or both ears. "RIMBP2 is a member of a family of proteins that act as binding partners of the presynaptic active zone proteins RIMs as well as for voltage-gated Ca2+-channels, such as CACNA1B and CACNA1D, the latter already known to be involved in deafness." (PMID 24454846, 2014).
hearing loss (1 paper, 2014). "A genotype-phenotype difference, with a slight improvement of threshold in the homozygous AA subjects, is evident for RIMBP2; interestingly, it maps within the DFNA41 locus associated with dominantly-inherited progressive hearing loss." (PMID 24454846, 2014).
hepatocellular carcinoma (1 paper, 2024). A malignant tumor that arises from hepatocytes. "RIMBP2 mRNA expression level correlates with the worst prognosis for lung squamous carcinoma patients and was found to be among 8 differentially expressed genes in lenvatinib-treated hepatocellular carcinoma." (PMID 39596218, 2024).
RIMBP2 also shares sentences with these, for which no sentence is quoted: Anxiety (2 papers); anxiety disorder (1); autism spectrum disorder (1); bipolar disorder (1); brain disorder (1); cancer (1); depression (1); pancreatic cancer (1); tumor (1).